MECOM (MDS1 and EVI1 complex locus)
Diseases named in the same sentence as MECOM in open-access papers (continued):
Sharing a sentence is not in itself a finding about the gene and the disease.
cancer (continued). "Furthermore, differentially expression of IRAK2 and MECOM genes has been reported in many studies in cancers or COPD." (PMID 36194576, 2022). "Importantly, these functional mutations affected genes that belong to cancer-related pathways and include the oncogenic FTH1 and tumor-suppressive MECOM." (PMID 34244513, 2021). "The remaining 28 ‘cancer’ genes identified as upregulated and hypomethylated, as with the acute RE analysis, this included those implicated in TGF-beta signalling (TGFB3, TGFBR2, LEF1 and MECOM) after chronic RE in human skeletal muscle." (PMID 30862794, 2019). "Notably, a similar frameshift mutation was found to occur in a mononucleotide repeat (A7) of PRDM3/MECOM gene in this cancer type." (PMID 30347759, 2018). "CovEx identified extra NCG cancer genes MECOM and NF1 and CGC cancer gene IKBKB." (PMID 28415609, 2017). "Furthermore, our results are confirmed by the literatures, with 6 out of top 10 features associated with specific cancers including NKIRAS1, CDKN2B, YTHDC2, MECOM, RBFOX1, and RAB6B." (PMID 33329723, 2020). "This work focused on the molecular mechanisms by which these two drugs inhibit cancer cell growth, particularly through histone modifications to regulate the inflammatory genes CXCL10 and MECOM." (PMID 40805064, 2025). "Intriguingly, we found that the protein expression levels of MECOM, PRDM5, PRDM10, and PRDM11 were generally higher in UCEC tissue compared to normal tissue, while the expression of PRDM1 was diminished in cancer tissue." (PMID 39468462, 2024). "The H-score levels of the protein expression levels of MECOM and PRDM11 were significantly higher in UCEC tissue, whereas the H-scores of PRDM1 and PRDM12 were weakened or undetectable in cancer tissue." (PMID 39468462, 2024). "Overall, the candidate gene set was significantly enriched for known cancer census genes (e.g. SGK1, MECOM, PRKCB) and known transcription co/factors (e.g. CACNA2D3, BMP4)." (PMID 36624125, 2023). "We examined 44 AML cell lines from the Cancer Cell Line Encyclopedia (CCLE) and stratified them based on MECOM expression." (PMID 36522544, 2023). "To find potentially approved drugs that target MECOM, RCN2, and MBNL3, we screened the herb database for related small molecules with anti-cancer effects." (PMID 36171401, 2022). "Cancer-related genes commonly amplified from 3q26 include PIK3CA, TBL1XR1, DCUN1D1, SOX2, MECOM, PRKCI, and TERC." (PMID 34436017, 2021). "However, our research further reveals the unique mechanisms by which MECOM regulates cell behavior in UCEC, deepening the understanding of its role in this specific cancer type." (PMID 39468462, 2024). "It implies that our observations of MECOM in UCEC, despite sharing similarities with findings in some cancers, require further investigation to understand the unique mechanisms of MECOM in regulating UCEC cell behavior and its varied roles across different cancer types." (PMID 39468462, 2024). "MECOM and PRDM family members play multifaceted roles in cancer." (PMID 39468462, 2024). "RNA sequencing analysis showed that human dedifferentiated acinar cells expressed genes in “Pathways of cancer” with a prominence of MECOM (EVI-1), a transcription factor that was not expressed by duct cells." (PMID 33762742, 2021). "From limited sample material, we detected integration events in 2,749 cells and found no integration events at genomic loci associated with clonal expansion after gene therapy near LMO2, IKZF1, CCND2, HMGA2, or MECOM, and no overrepresentation near cancer-related genes." (PMID 39532107, 2025). "In addition to immune-fluorescent staining of CTCs, we performed fluorescence in situ hybridization (FISH) in some selected cases to investigate the copy number of the stem-cell like fusion genes MECOM/HHLA1 and to pinpoint CTCs as cancer cells in case of doubt." (PMID 29290959, 2017).
cancer (continued). "The presence of MECOM and/or HHLA1 gains in all CTC samples investigated confirmed the specificity of the multi-marker staining, and furthermore allowed us to ascertain that “ambiguous” cells corresponded to cancer cells, thus enabling us to extend the CTC count." (PMID 29290959, 2017). "In addition, the miR-133a-3p target genes: MDS1 and EVI1 complex (MECOM) may also play a significant role in pathways related to cancer." (PMID 27825300, 2016). "The mechanisms of enhancer deregulation observed in other cancer types, including TAD boundary disruptions and the creation of de novo (super‐) enhancers, may explain overexpression of MECOM or other oncogenes in AML without enhancer hijacking upon translocation." (PMID 39853740, 2026).
tumor (36 papers, 2010 to 2025). "In contrast, infection by pHV LV resulted in identification of 3762 (seven-fold increase) DEG of which 81 oncogenes and 82 tumour suppressor genes, that included MECOM, LMO-2 and BRAF genes previously associated with genotoxicity." (PMID 40664913, 2025). "Using NIH-OVCAR3 cells bearing doxycycline-inducible shRNAs against PAX8 or MECOM confirmed that PAX8 silencing leads to profound regression, while MECOM loss induces tumor growth arrest/stasis." (PMID 33903593, 2021). "The tumor origin of these cells was confirmed by the identification of shared mutations in the MDS1 and EVI1 complex locus, myosin 11, and neurofibromin 1, as well as the platelet-derived growth factor receptor Alpha and the amplification of the endothelial growth factor receptor." (PMID 35806478, 2022). "Further, qRT-PCR analysis of extracted mRNA from the E-JIB04 and control-treated mice tumor tissues showed decrease in levels of MECOM." (PMID 40664642, 2025). "Furthermore, MECOM is one of the genes with the highest genetic variation, including amplification, deep deletion, high mRNA expression, and missense mutations, which may indicate its key role in tumor development." (PMID 39468462, 2024). "The TTC28-MECOM fusion gene with CN gains of MECOM in tumor specimen was validated by PCR using the primer set from TTC28 and MECOM." (PMID 39158654, 2024). "Changes in MECOM also affect the cell's migration ability, potentially impacting tumor invasion and metastasis." (PMID 39468462, 2024). "Transwell migration assay results showed that compared to the control group, the migration ability of cells in the MECOM overexpression group was significantly enhanced, possibly due to MECOM overexpression promoting tumor cell invasion and metastasis." (PMID 39468462, 2024). "Conversely, cell migration ability was significantly reduced in cells with MECOM knocked out, inhibiting tumor cell invasion and metastasis." (PMID 39468462, 2024). "Approximately 4% of patients with acute myeloid leukemia (AML) have neoplasms associated with rearrangements of the myelodysplasia syndrome 1 (MDS1) and ecotropic viral integration site 1 (EVI1) complex locus (MECOM)." (PMID 36672407, 2023). "The results show that the expression of MECOM in tumor patients is positively correlated with the infiltration level of CD8 + T cells, neutrophils, and T cell gamma delta." (PMID 36171401, 2022). "From the results of the tumor-associated genes analysis, the most significant ten tumor- associated genes such as SNAI2, VCAM, MMP2, BRCA1, PARP1 and MECOM were closely associated with UCPs." (PMID 35090503, 2022). "While we do also observe in our PAX8 ChIP-seq dataset a strong enrichment for TEAD motifs, our study focuses on MECOM interaction as we readily identified it in BioID experiments and demonstrate that MECOM is necessary for in vivo tumor growth." (PMID 33903593, 2021). "Previous scientific evidence showed that the MECOM acts as an oncogene regulating signaling pathways that lead to increased tumor proliferation." (PMID 33432064, 2021). "They showed that MECOM is highly expressed in 41.9% of GBM tumor samples using immunohistochemistry." (PMID 32962037, 2020). "A multi-marker immunostaining was established and further complemented by FISH on CTCs and tumor/metastasis tissues using probes for stem-cell like fusion genes MECOM and HHLA1." (PMID 29290959, 2017). "Notably, studies have found that MECOM acts as a tumor suppressor gene, thus potentially serving as a target for the anticancer effects of W6134 and XY018." (PMID 40805064, 2025). "Moreover, several genes from the G2M downregulated gene set, including MKI67, MCM2, CCND1, and their STRING-interacting genes MECOM, TYMS, and MTHFR, are associated with neoplasms." (PMID 37958729, 2023).
tumor (continued). "This revealed that MECOM, PAX8, SOX17 and WT1 are lineage-enriched, super-enhancer associated master regulators whose cooperative DNA-binding patterns and target genes are re-wired during tumor development." (PMID 37090516, 2023). "Similarly, the increased expression of LINC00519 hindered the expression of the downstream miRNA, which led to the overexpression of MECOM and appeared to affect the behavior of tumor cells." (PMID 36171401, 2022). "The potential mechanism of MECOM and PRDM16, especially MECOM, in terms of tumor progression, prognosis, and immune cell infiltration in LUAD, however, remains unclear." (PMID 35174083, 2022). "The fact that the genes positively regulated by PAX8 and MECOM also stratify patients with poorer prognosis suggests that indeed PAX8 cooperates with MECOM to regulate a gene expression program that promotes aggressive tumor phenotypes." (PMID 33903593, 2021). "The expression levels of particular MECOM isoforms propose that the N-terminal region of PRDM3 confers a tumor suppressor function, while the shorter EVI1 isoform is overexpressed in several malignancies and could have oncogenic properties in both myeloid and solid tumors." (PMID 32290321, 2020). "Differential motif analysis nominated AHR and FOXM1 as the most significant TF motif gained by the T>C change in the MECOM promoter, and RNA-seq data analysis confirmed the expression of AHR and FOXM1 in the tumor sample." (PMID 40355593, 2025). "Collectively, our data highlights that tumor-specific epigenetic remodeling is tightly related to MECOM, PAX8, SOX17 and WT1 activity and these transcription factors are targetable in a tumor-specific manner through transcriptional inhibitors." (PMID 37090516, 2023). "To better elucidate the impact of MECOM, RCN2, and MBNL3 on the tumor microenvironment and immunotherapy, we conducted an immune infiltration analysis." (PMID 36171401, 2022). "At the genome level, gains in the MECOM and HHLA1 loci were observed in the primary tumor and the metastases, as well as in just 25% and 50% of the CK7/18-positive CTCs, respectively." (PMID 29290959, 2017). "Additionally, in CMT-N7 cells, TNF/MAPK inflammatory pathway-related genes such as CXCL10 and MECOM were significantly upregulated following W6134 and XY018 treatment, exhibiting favorable anti-tumor effects, which aligns with previous findings." (PMID 40805064, 2025). "Notably, some genes (e.g., MET, HSPA6, ID1, MECOM, POU2AF1, SFRP4, CDH1) exhibited expression predominantly in tumor cells and a limited number of other cell types." (PMID 40954493, 2025). "MECOM was upregulated in UCEC tissues, influencing tumor cell behavior significantly." (PMID 39468462, 2024). "In addition, four genes (BAIAO3, MECOM, MAP3K13, and NOS) were found to have decreased expression in tumor from patients who experienced recurrence compared to those who did not." (PMID 34729947, 2021). "Targeting the MAPK signal transduction pathway through the targeting of the FGF2, FGF9, MECOM, PLA2G4C and PRKACB might increase tumor responsiveness to irinotecan treatment." (PMID 28749961, 2017). "We could not find any specific inhibitor targeting MECOM, hence, an alternative strategy to target tumor cells expressing high MECOM levels was envisaged." (PMID 40664642, 2025). "In conclusion, targeting the MAPK signal transduction pathway through the targeting of FGF9, FGF2, MECOM, PRKACB and PLA2G4C might increase tumor responsiveness to irinotecan and improve patient survival thus being therapeutically and prognostic significant in CRC patients." (PMID 28749961, 2017). "In addition, MECOM mRNA expression is also higher in tumor tissues than in normal tissues." (PMID 32962037, 2020).
hematologic malignancies (4 papers, 2019 to 2024). "One report linked MECOM mutations with hereditary hematologic malignancies, after two out of four family members with MECOM mutations and radioulnar synostosis developed MDS in adulthood." (PMID 38473358, 2024). "Another report suggested MECOM being a candidate gene for hereditary hematological malignancies." (PMID 38245683, 2024).
genetic disease (2 papers, 2023 to 2025). "Here, we have studied a rare genetic disorder due to MECOM haploinsufficiency, characterized by an early-onset absence of HSCs in vivo." (PMID 36522544, 2023).
infection (2 papers, 2023 to 2025). The state of being infected such as from the introduction of a foreign agent such as serum, vaccine, antigenic substance or organism. "Infection of MECOM-edited HSPCs with MECOM virus led to supraphysiologic levels of MECOM expression, which was sufficient to rescue the LT-HSC loss observed after MECOM editing." (PMID 36522544, 2023).
bacterial infections (1 paper, 2023). "Recent findings indicated that the MECOM is upregulated by inflammatory stimuli, including bacteria, and that mutations in the MECOM make mice more susceptible to bacterial infections." (PMID 37821814, 2023).
hematologic neoplasms (1 paper, 2025). "Structural abnormalities resulting in chimeric gene fusion between MECOM locus at 3q26.2 and various partner genomic loci, with either known or unknown gene content in hematologic neoplasms, as documented in the public databases and literature." (PMID 40255434, 2025).
metabolic disorders (1 paper, 2025). "Dysfunction of the human orthologs of Ham, PRDM16 (Mel1) and PRDM3 (Evi1, MECOM), has been found in a variety of human abnormalities including congenital diseases, metabolic disorders and cancers." (PMID 40613556, 2025).
MECOM also shares sentences with these, for which no sentence is quoted: acute promyelocytic leukemia (2 papers); cancers of the central nervous system (2); Hypomagnesemia (2); acute leukemia (1); acute megakaryoblastic leukemia (1); adenocarcinoma (1); anemia (1); autoimmune disease (1); Autoimmunity (1); B-cell chronic lymphocytic leukemia (1); bone marrow failure syndrome (1); carcinosarcoma (1); cardioembolic stroke (1); cardiovascular disease (1); Congenital thrombocytopenia (1); cutaneous melanoma (1); diffuse large B-cell lymphoma (1); ductal carcinoma in situ (1); esophageal cancer (1); esophageal squamous cell carcinoma (1); Fanconi anemia (1); glioma (1); head and neck squamous cell carcinoma (1); heart failure (1); hepatoblastoma (1); hepatocellular carcinoma (1); inflammatory bowel disease (1); inherited bone marrow failure syndrome (1); invasive breast carcinoma (1); ischemic stroke (1).
A further 15 diseases each share a sentence with MECOM in 1 paper.